SPATA31D4 (SPATA31 subfamily D member 4)
Description:
May play a role in spermatogenesis.
Synonyms: FAM75D4; FLJ43859
Tractability: Antibody: UniProt predicts a signal peptide or a membrane-spanning region.
Gene: Protein-coding gene on chromosome 9 (81,928,428 to 81,934,998, forward strand). Ensembl gene ENSG00000189357.
Subcellular location: Membrane
Gene Ontology:
Cellular component: membrane
Genetic constraint (gnomAD): Loss-of-function variants: 1 observed, 0.29 expected, observed/expected ratio (o/e) 3.45. That is too few expected variants to judge how well the gene tolerates losing a copy. Missense variants: 66 observed, 136.47 expected, observed/expected ratio (o/e) 0.48, 90% interval 0.4 to 0.59. Synonymous variants: 22 observed, 47.44 expected, observed/expected ratio (o/e) 0.46, 90% interval 0.33 to 0.66.
Homologues: Orthologues: mouse Spata31f3 (5% identical). Paralogues in human: SPATA31D3 (99% identical), SPATA31D1 (91% identical), SPATA31A6 (26% identical), SPATA31A1 (26% identical), SPATA31A3 (26% identical), SPATA31A5 (26% identical), SPATA31A7 (26% identical), SPATA31E1 (22% identical), SPATA31C1 (21% identical), SPATA31C2 (21% identical), SPATA31F1 (17% identical), SPATA31F3 (3% identical).